CD44 (CD44 molecule (IN blood group))
Diseases named in the same sentence as CD44 in open-access papers (continued):
Sharing a sentence is not in itself a finding about the gene and the disease.
breast carcinoma (continued). "Among breast cancer circulating tumor cells, CD44+CD24+ALDH1+ subpopulation show an increased tumorigenic potential, while EpCAM+CD44+CD47+MET+ subset denotes cells with high metastatic ability." (PMID 33968778, 2021). "It should be noted that both CD44 and RHAMM are expressed on the cell surface of primary breast cancer cells." (PMID 34338608, 2021). "Similar to breast cancer, the majority of CTCs enriched from NSCLC-BM patient’s blood showed a strong expression for both CD74 (13/27 CTCs) and CD44 (15/27 CTCs)." (PMID 34209696, 2021). "EpCAM+, CD44+, CD24- CSCs were 10-fold more likely to induce tumors compared to EpCAM-, CD44+, CD24- CSCs in breast cancer." (PMID 33889547, 2021). "Previous studies have shown that after chemo- and radiotherapy, breast cancer cells are enriched in cells with a CSC-like phenotype characterized by resistance to therapies and high CD44 and CD166 expression, two well-recognized cancer stem cell markers." (PMID 34576263, 2021). "Correspondingly, ectopic lnc408 obviously augmented both mRNA and protein expressions of breast cancer stemness markers (e.g., SOX2, Nanog, and CD44)." (PMID 33934099, 2021). "Autophagy maintains the expression of breast CSC CD44+/CD24−/low fractions by secreting CD24 and IL-6 in breast cancer." (PMID 34149413, 2021). "89Zr-based PET imaging of CD44 was first explored in a study that used an anti-human Ab called RG7356, and demonstrated high uptake in human breast cancer xenografts of mice." (PMID 33594192, 2021). "We previously reported that PrPc promotes multidrug resistance in ER + breast cancer cell line MCF7/ADR by interacting with P-gp and CD44." (PMID 33413403, 2021). "CD44 is one of the main HA receptors, and its overexpression correlates with cell migration, EMT and metastasis in breast cancer." (PMID 34944559, 2021). "The combination of CD44 and CD24 or aldehyde dehydrogenase 1 (ALDH1) is a representative cancer stem cell marker in breast cancer." (PMID 33861751, 2021). "Using a small molecule inhibitor of IRS-1, NT157, we showed striking reduction of ER+ breast cancer tumoursphere formation and expression of stem-like markers (ALDH1, CD44/CD24)." (PMID 33144693, 2021). "Single-cell RNA profiling of CSCs from breast cancer cells, where CD44 is considered as a CSC marker, has revealed some significant information regarding CD44 expression in the context of hypoxia and the hierarchy of CSCs." (PMID 34150761, 2021). "We previously demonstrated that the anti-CD44 mAb, H4C4 stained all three tested tumorigenic cell lines, the breast cancer cell line MB-231, the melanoma cell line HTB-66, and the glioblastoma cell line U87." (PMID 33891595, 2021). "Aberrantly upregulated in multiple carcinomas, like breast cancer, lung adenocarcinoma, colorectal cancer, prostate cancer, and RCC, CD44 takes part in various physiological processes including tumorigenesis and cancer progression." (PMID 34934046, 2021). "For breast cancer, two distinct CSC populations exist and are typically defined by CD44+/CD24- cell surface marker expression or increased aldehyde dehydrogenase (ALDH) activity." (PMID 35127497, 2021). "For example, the basal breast cancer cell line JIMT-1, which is HER2-high, is highly enriched for CD44+/CD24− cells that can quickly develop de novo resistance to trastuzumab in late-passages." (PMID 34575017, 2021). "In agreement with our observations, forced overexpression of HSF-1 increased mammosphere-forming ability as well as CD44, Sox2 and ALDH1 expression, and conferred drug resistance in breast cancer, while HSF-1 knockdown attenuated these phenomena." (PMID 34775489, 2021). "High expression of CD47, CD49c, CD44, and ALDH1A1 suggests the breast cancer origin of the KAIMRC2 cell line." (PMID 34073849, 2021). "In cervical cancer and breast cancer cells, the activation of β-catenin along with AKT signalling pathways were correlated with the upregulated expression of CD44." (PMID 34944493, 2021).
breast carcinoma (continued). "In the breast cancer BM cohort, all seven CTC positive patients showed a mostly strong or intermediate expression for CD74 (39/40 CTCs) as well as for CD44 (3/40 CTCs)." (PMID 34209696, 2021). "Flow cytometry was used to assess the expression of putative breast cancer stem cell markers of CD44/CD24 in MDA‐MB‐231 cells and displaying a proportion of 93.77% ± 4.04% of the CD44+/CD24− subpopulation." (PMID 34320274, 2021). "It was also shown that luteolin inhibited various stem cell markers such as CD44, ALDH1, and others in breast cancer cells." (PMID 34884848, 2021). "The activation of different cell signals of HA by CD44, as well as by RHAMM in breast cancer, is well documented." (PMID 34070901, 2021). "These markers are expressed in a tissue-specific manner e.g., CD44, CD24 and ALDH are specific to breast cancer, CD34, CD8 to leukaemia, CD133 to colon cancer, CD44 to head neck cancer and CD90 to liver cancer." (PMID 34638469, 2021). "Recently, our group has found that the expression level of USP37 is exceptionally upregulated in CD44+/CD24- phenotype breast cancer stem cells, and can regulate the stemness of breast cancer cell through its interaction with GLI-19." (PMID 33390801, 2021). "More studies exhibit that CSCs are present in different solid tumors, including breast cancer, which is characterized by a CD24 −/CD44+ cell surface marker." (PMID 34947829, 2021). "First, primary human tumor cells were isolated from TNBC breast cancer patients and primary CD44+/CD24- CSCs and CD44-/CD24- tumor cells were purified by flow cytometry sorting." (PMID 34318746, 2021). "Genes related to proliferation (MKI67, CCNA2), differentiation (EPCAM, CDH1), epithelial to mesenchymal transition (VIM, SNAI2), pluripotency and breast cancer stem cells (SOX2, NANOG, CD44) were included." (PMID 34090457, 2021). "CD44 has been shown to be expressed on metastasis-initiating CTCs and CTC clusters in breast cancer, thereby promoting tumorigenesis and metastasis." (PMID 34209696, 2021). "CD44 also interacts with other membrane proteins, such as EGFR and HER2, to promote the metastasis of breast cancer." (PMID 33801148, 2021). "Thus, the dormant CD44-/CD24- breast cancer cells that have previously been colonized in the metastatic site may be able to spontaneously convert into CD44+/CD24- breast CSCs to regain their potent proliferative ability and drug resistance, resulting in delayed breast cancer metastasis." (PMID 34318746, 2021). "OSM exposure increased CD44 and Snail expression and repressed CD24, Claudin-1 and E-cadherin in breast cancer cells, while promoting migration and 3D tumour sphere formation." (PMID 34361105, 2021). "Given that CD44 is a prominent breast cancer stem cell marker, our results suggest that CAP affects stem cell niche and suppresses breast cancer cell stemness." (PMID 35111687, 2021). "For example, the interaction of LMW-HA with CD44 and TLR enhanced the production of IL-1β/IL-8 via the subsequent activation of MyD88/NF-κB and finally promoted the invasiveness of breast cancer cells." (PMID 33986244, 2021). "As an example, ESA+/CD44+/CD24−, and ALDH1+ were detected in breast cancer stem cells (BCSCs); CD133+ in colon, glioblasoma, gastric and lung; EpCAM, CD133/EpCAM, CD90+ ESA+CD133+ CD44+CD24+ in liver; and ESA+/CD44+/CD24+ in pancreatic CSCs." (PMID 34051847, 2021). "For example, in breast cancer, cells with TPC properties can be isolated by ALDH or CD44+/CD24– markers." (PMID 34618689, 2021). "It has been proposed that CD44+CD24−/low breast cancer cells have the stem/progenitor cell properties, which is called breast CSC-like cells or breast cancer stem cells (BCSCs)." (PMID 34715882, 2021). "In the breast cancer cell lines, the conversion from non-invasive epithelial-like CD44+CD24+ cells to invasive mesenchymal CD44+CD24− progeny was also found to be activin/nodal-dependent." (PMID 34356885, 2021).
breast carcinoma (continued). "In breast cancer, there are two major CSC populations which are characterized by CD44+/CD24− and ALDHhigh markers." (PMID 34680503, 2021). "A special remark is made to near-infrared photoimmunotherapy directed at CD44 and CD133, which are not only considered markers of CSCs in breast cancer and glioblastoma but also in HNSCC." (PMID 34307351, 2021). "Similar results were also demonstrated in BT-474 luminal B breast cancer cells from sphere-formation assay and flow cytometry analysis of CD24−/CD44+ expression." (PMID 33986289, 2021). "Again, PrPC/CD44 interaction promotes chemoresistance and tumor progression in MDR breast cancer cells." (PMID 33418999, 2021). "TNBC and luminal breast cancer patients with a higher frequency of CD44-/CD24- cells had a worse DFS, compared than those with a lower frequency of CD44-/CD24- cells following standard therapies." (PMID 34318746, 2021). "Here, we review the well–regulated inflammatory and fibrogenic functions of HA polymers and two HA receptors—CD44 and RHAMM (HMMR)—in cutaneous wound repair and consider evidence that these functions also contribute to the progression of breast cancer." (PMID 34827550, 2021). "This is consistent with prior research findings that HMGA2 induces sphere formation and promotes the expression of cancer stem cell markers, including CD44, ALDH1, CD133 in gastric and breast cancer." (PMID 34680349, 2021). "The specific ability of Ad‐VT in killing breast cancer stem cells was studied by CCK‐8 assay and detection of the presence of CD44+CD24− cell subgroup." (PMID 33305893, 2021). "Although CD34+CD38-6, 7, CD133+8 and CD44+CD24-9-11 have been widely used as CSCs markers in human acute myeloid leukemia, brain tumor and breast cancer respectively." (PMID 31892981, 2020). "MiR-7 also modulated the miR-92b/Slug/ESA (epithelium-specific antigen) axis and reduced CD44 and Slug expression, resulting in a decrease in cancer cell stemness and the BCSC subset in breast cancer." (PMID 32143670, 2020). "In breast cancer, BCSCs are defined by expression of ESA, CD44 and low CD24 expression (ESA+/CD44+/CD24-), and high tumorigenic capabilities." (PMID 32673341, 2020). "High aldehyde dehydrogenase activity (ALDH)bright and CD44+/CD24−/ESA+ cancer cells, previously shown to have BCSC properties, were isolated from human MDA-MB-231 and UACC-812 breast cancer cell lines by flow cytometer." (PMID 32138738, 2020). "The authors reported that doxycycline decreased CD44+ positivity, a CSC marker, suggesting the possible efficacy of this drug in resistant breast cancers." (PMID 33217901, 2020). "Furthermore, 41% of ER+/PR+ and/or HER2+ locally metastatic breast cancers expressed ΔNp63/p40, and these cells commonly accounted for <1% of the metastatic tumour cell population that localised to the tumour/stroma interface, exhibited an undifferentiated phenotype and were CD44+/ALDH−." (PMID 31591823, 2020). "The genetic inhibition of autophagy decreases the proportion of breast cancer cells with the CD44+/CD24–/low CSC-like phenotype, signifying a role of autophagy in maintaining typical CSCs in breast cancer." (PMID 32391363, 2020). "Progesterone has also been reported to downregulate the expression of miR-141, a member of the miR-200 family of tumor suppressors, leading to an increase in the number of stem-like breast cancer cells (CK5+ and CD44+ cells)." (PMID 33014829, 2020). "Reduced CTGF expression led to increased CD44, SPARC, and FN1 expression in mesenchymal transformed breast cancer cells." (PMID 33087801, 2020). "TNBC forms the largest part of the basal-like subtype (~80%), which is the most aggressive molecular subtype with the highest content of breast cancer stem cells (BSCSs) characterized by the most common BCSC biomarkers, CD44+/CD24−/low and ALDH1+." (PMID 33327542, 2020).
breast carcinoma (continued). "The fluorescence–SERS duplex imaging of MDA-MB-231 breast cancer cells, which co-express CD24 and CD44 markers at their surfaces, confirmed their colocalization in the cells." (PMID 33256052, 2020). "We evaluated the heterogeneity of stem CTCs by their CD44, ALDH1, and CD133 expression depending on N-cadherin expression in breast-cancer patients." (PMID 32316333, 2020). "A high miR-210 expression was also detected in CD44+/CD24− MCF-7 cells and human CD44+/CD24− breast cancer cells." (PMID 32961774, 2020). "First, we evaluated the ALDH activity, the expression of BCSC genes (Nanog, Sox2 and Oct4), multiresistance pumps (ABCG2, ABCC1 and ABCB1) and the BCSC frequency (CD44+CD24+CD49+EPCAM+) in three human breast cancer cell lines." (PMID 33184339, 2020). "High expression of CD44 and low expression of CD24 (CD44+/CD24−) are useful for identifying and isolating the cells with stem-like properties in normal mammary tissues and breast carcinomas." (PMID 33217982, 2020). "In solid malignancy, CD44+ CD24−ve cells, in a variety of solid malignancies including breast cancer, have been classified as CSCs." (PMID 32684928, 2020). "ALDHbright and CD44+/CD24−/ESA+ tumor cells, previously shown to have BCSC properties, were isolated from human MDA-MB-231 and UACC-812 breast cancer cell lines by FACS." (PMID 32138738, 2020). "In CD44+/CD24- cell lines and the primary culture of patient breast cancer cells, elevation in both expression and phosphorylation of ATM were found." (PMID 33680952, 2020). "In our previous research, we performed miRNA profiling between sorted CD44+CD24−/low BCSCs and the control MCF-7 breast cancer cells." (PMID 33008330, 2020). "The intracellular domain of CD44 can act as a co-transcription factor for RUNX2, inducing MMP-9 expression in breast carcinoma cells." (PMID 32204402, 2020). "CD44-ICD has been shown to interact with the master regulator of osteoblastogenesis, RUNX2, in the nucleus of breast cancer cells." (PMID 33062960, 2020). "In breast cancer research, distant metastases tend to develop when TGFBI and CD44 were expressed at high levels, which verifies the relationship between TGFBI and immune responses." (PMID 33614494, 2020). "Both populations were highly tumorigenic – as few as 50 to 100 CD44+/CD24− and CD133+ breast cancer cells induced tumors in NOD/SCID mice – and expressed stem cell associated genes, including Oct4, Notch1, Aldh1, Fgfr1 and Sox1." (PMID 32430004, 2020). "Prognostic significance was demonstrated for the expression of TWIST1, ALDH1, CD44, CD24 in CTCs from early breast cancer." (PMID 32121386, 2020). "Among all dopamine receptors, D1R expression is upregulated in breast cancer cells’ population that displays a stem cell phenotype (CD44+ and CD24-) compared to the differentiated breast cancer cells." (PMID 33147760, 2020). "In breast cancer cell lines, such as MDA-MB-231, a subset of markers, including CD44+/CD24− has been shown to enrich CSC27." (PMID 32680999, 2020). "Tumor spheres were cultured by the suspension method, and the CD44+CD24-/low subpopulation, which is recognized as a special stem-like phenotype of breast cancer, was significantly increased in spheres, which was consistent with our previous findings." (PMID 33457406, 2020). "In accordance, we also found a significant enrichment of the BCSC markers CD44, CD49f, P-cadherin, EpCAM, and ALDH1 in human breast cancer brain metastasis when compared with unmatched primary tumors previously analyzed by our group." (PMID 33182375, 2020). "The findings from this study uncover the molecular mechanisms by which miR-7 inhibits XIST, modulates the miR-92b/Slug/ESA axis, and decreases the RELA and CD44 expression, resulting in a reduced BCSC subset and breast cancer growth inhibition." (PMID 32143670, 2020). "Breast cancer stem cells (BCSC) have a number of markers, such as CD44, CD24, aldehyde dehydrogenase 1 (ALDH1), among others." (PMID 33102470, 2020).
breast carcinoma (continued). "The miRNA profile between breast cancer stem cells (BCSCs, CD44+CD24−/low) and control MCF-7 breast cancer cells was obtained in a previous study." (PMID 33008330, 2020). "GSK1016790A produced a general trend in EMT marker mRNA levels in PMC42LA breast cancer cells with significant increases in Snail, vimentin, AXL, SERPINE1, and CD44." (PMID 33322037, 2020). "CD44+ CD24−/low ESA+ (epithelial surface antigen, also known as EpCAM) cells were identified as CSCs in a number of solid malignancies such as breast cancer." (PMID 32684928, 2020). "Similar to CD44+/CD24−/low cells, ALDH1+ BCSCs are more frequently found in basal-like breast cancer tumors than in luminal type tumors and cell lines; however, ALDH1+ cells are also commonly found in the HER2+ BC subtype." (PMID 33327542, 2020). "BCSCs present in two well-established human breast cancer cell lines, MDA-MB-231 and UACC-812, identified and isolated by flow cytometry as either ALDHbright or CD44+/CD24−/ESA+ cells were used in this study." (PMID 32138738, 2020). "We initially evaluated by flow cytometry the levels of the well-known CSC immunophenotype CD44+CD24− in MDA-MB-231 and MCF-7 human breast cancer cell lines grown on a 2D surface or within Col-I gels." (PMID 32435546, 2020). "Using TA3 murine mammary carcinoma cells, Yu and Stamenkovic showed that MMP9 is localized on the cell surface in a CD44-dependent manner and stimulates proteolytic cleavage of TGF-β, and they proposed a novel role for MMP9 in TGF-β-dependent tumorigenesis." (PMID 33172999, 2020). "In breast cancer, treatment with a vitamin D analog, BXL1024, reduced breast cancer stem-like cells population CD44+/CD24-/low and CD49f+/CD24-/low, identified as markers of tumor-initiating cells." (PMID 32560347, 2020). "Phuc and colleagues performed a study in which the stem cells of breast cancer CD44+CD24− were isolated from breast tumors; the expression of CD44 was downregulated with siRNAs followed by treatment with specific antitumor concentrations." (PMID 32684928, 2020). "CD44+/CD24-/low CSCs, derived from breast cancer, exhibit migration potential that increases with tumor grade, while a human CD44+ CD24-/low Lin- and mouse Thy1+ CD24+ Lin- CSC-enriched population exhibits low ROS levels and high expression of anti-ROS genes." (PMID 32658903, 2020). "Several studies have reported that exosome biomarkers (such as CD44, CD47, CXCR4, Del-1, HER2, and KDR) can be used for early diagnosis and prognosis of breast cancer patients." (PMID 32826923, 2020). "Based on this data, the expression of BCSC markers (CD44, CD49f, P-cadherin, EpCAM, and ALDH1) was determined and found to be significantly enriched in breast cancer brain metastases when compared to primary tumors." (PMID 33182375, 2020). "Inhibition of ATM increased radiation sensitivity of the isolated CD44+/CD24- cell, which suggests that ATM is a potential target to improve radiation sensitivity in breast cancer therapy." (PMID 33680952, 2020). "Among the CSC surface markers, CD44 and CD24 phenotype have been widely employed in breast cancer research." (PMID 32545405, 2020). "For example, it is unnecessary to call “CD44(+)/CD24(-) and ALDH1(+)” breast cancer cells as CSC 843-846, since “CD44(+)/CD24(-) and ALDH1(+)” defines them more specifically and clearly than the equivocal “CSC”." (PMID 32226506, 2020). "CD44 is overexpressed in breast tumor cells, and the ratio of CD44 to CD24 has been used as a marker for stem cells in breast cancer." (PMID 32699630, 2020). "Human breast cancer stem cells can be recognized by several surface antigen markers, such as CD24-/CD44+." (PMID 33211707, 2020). "CD44 and CD24 have been suggested as suitable markers for the identification of breast cancer stem cells, whereby the phenotype of tumorigenic mammary tumor cells was determined as CD44+/CD24−/low." (PMID 32430004, 2020).